KRAS (KRas proto-oncogene, GTPase)
Diseases named in the same sentence as KRAS in open-access papers (continued):
Sharing a sentence is not in itself a finding about the gene and the disease.
lung cancer (continued). "In patients with lung cancer harboring KRAS mutations, the most mutations occur in codon 12, whereas mutations in codons 13 and 61 are less frequent." (PMID 31612108, 2019). "KRAS further activates the Ras/Raf/MEK/ERK pathway, and it is estimated that 15% of lung cancer specimens harbor KRAS mutations." (PMID 30935143, 2019). "Next, we investigated signaling events that underlie HSP90 requirement in drug-resistant KRAS-mutant lung cancer cells." (PMID 31431614, 2019). "This has been shown for KRAS-mutant acute myeloid leukemia, colon and lung cancer cells that lost the remaining (tumor-suppressive) wild-type KRAS allele." (PMID 32039027, 2019). "In lung cancer, KRAS mutations occur primarily in adenocarcinoma, whereas they are only rarely seen in squamous cell carcinoma." (PMID 31612108, 2019). "We confirmed that only p65BTK, and not p77BTK, was expressed in NSCLC and we showed that p65BTK over-expression correlated with mutations in KRAS or the RAS/MAPK pathway both in in vitro and in vivo models of lung cancers with mutated KRAS." (PMID 31200752, 2019). "The prevalence of KRAS mutations in the lung cancer is 20% to 30%, 85% of which affect codon 12, and these mutations are associated with poor prognosis in NSCLC patients." (PMID 31636509, 2019). "In this study, we aimed to explore EGFR knockout as a therapeutic option in EGFR wild-type and KRAS mutated lung cancer cells." (PMID 30935067, 2019). "Lung cancer cell lines with KRAS mutation were relatively more sensitive to KRA-533 than cell lines without KRAS mutation." (PMID 30971271, 2019). "Only a subset of KRAS mutated colon, pancreatic and lung cancer depends on MEK/ERK signaling for proliferation, although the cells responds to MEK inhibition with reduced pERK." (PMID 30795553, 2019). "Lung cancer patients with KRAS mutation(s) have a poor prognosis due in part to the development of resistance to currently available therapeutic interventions." (PMID 30971271, 2019). "In lung cancer, KRAS is most frequently mutated in lung adenocarcinoma (LUAD), where it is altered in 33% of patients." (PMID 31519898, 2019). "This study is the first to describe the imaging differences between lung cancer patients with KRAS and EGFR mutations using DESCT according to our knowledge." (PMID 31783917, 2019). "Taken together, the molecular testing of EGFR and KRAS mutations for lung cancer patients has offering advantages for guiding personalized therapy, providing a better patient selection and stratification for clinical management." (PMID 30824880, 2019). "Our results confirm previous reports that EGFR mutations are more prevalent than KRAS in Chinese lung cancer patients." (PMID 31369215, 2019). "For example, in the case of lung cancer, the prevalence of KRAS mutations in tissue ranges from 20–25% in the Western Hemisphere." (PMID 31581267, 2019). "In particular, EGFR and KRAS mutations have been rarely found in the same tumours in early studies of genetic alterations in lung cancer and KRAS mutations are regarded as a biomarker of resistance to EGFR TKIs." (PMID 30857358, 2019). "Krukovine effectively inhibited KRAS downstream signaling and induced G1 arrest and apoptosis to exert a cytotoxic effect on KRAS-mutated lung cancer cells lines." (PMID 30186180, 2018). "On the other hand, inactivating BRAF mutations have been identified in a subset of KRAS-activated lung cancers." (PMID 29690599, 2018). "KRAS is also a key biomarker in lung cancer as it is the most common alteration in NSCLC with mutations in KRAS occurring in approximately 30% of patients." (PMID 29765524, 2018). "The most prevalent mutated region of KRAS in lung cancer is codon 12 (exon 2) with 75% frequency, whereas mutations in other regions of KRAS are less frequent including codon 13 (exon 2) and codon 63 (exon 3)." (PMID 30048458, 2018).
lung cancer (continued). "Circulating DNA samples were obtained from the plasma of 72 patients with lung cancer, which were identified based on six mutation sites (G12S, G12R, G12C, G12D, G12A, and G12V) of codon 12 of the KRAS gene." (PMID 30080912, 2018). "The best described mechanism of primary resistance is a mutation in the KRAS oncogene which is present in 20 to 30% of lung cancer patients." (PMID 30337598, 2018). "Results showed that krukovine inhibited the growth of H460 and A549 in a time-dependent manner, while have less cytotoxicity effect on non-KRAS mutation lung cancer cell line H1299 and normal lung cell CCD19-Lu." (PMID 30186180, 2018). "Drugs that specifically block the most frequent KRAS mutation in lung cancer (p.Gly12Cys) are under development." (PMID 29890761, 2018). "We further examined if deltarasin can also induce cytotoxic effects on lung cancer cells with KRAS mutations, since lung cancers occur with much higher frequency than pancreatic cancers in the clinic." (PMID 29440631, 2018). "Other studies have shown that KRAS mutations and other cooperating mutations determine a metabolic reprogrammation of lung cancer cells, determining some vulnerabilities in these cells, potentially amenable to selective targeting." (PMID 30060526, 2018). "We found that the abundance measurements (expression and proportion) for the K-Ras4A isoform are strongly associated with the presence of KRAS mutations as well as a positive prognosis for lung cancer patients harboring KRAS mutations." (PMID 29504894, 2018). "Since KRAS is a well-known oncogenic driver in lung cancer, we further compared OS according to the mutational states of the gene in each group." (PMID 29504894, 2018). "Although KRAS mutations were identified in lung cancer, there have been very few trials addressing NSCLC patients with KRAS mutations, leading to no positive therapies." (PMID 30680072, 2018). "Another in vitro study showed the effectiveness of HSP90 inhibition in several KRAS‐mutated non‐small cell lung cancer (NSCLC) lines by ganetespib – a non‐geldanamycin analog with less toxic side effects." (PMID 29797762, 2018). "In our study, we found that deltarasin treatment caused the conversion of LC3-I to LC3-II in both KRAS-dependent lung cancer cells, as shown by the increases of GFP-LC3 puncta cells." (PMID 29440631, 2018). "A549 and H358 cell lines, which harbor KRAS G12S and G12C point mutations respectively, were used with normal lung fibroblast CCD19-Lu and a BRAF mutation lung cancer cell line, H1395, providing KRAS wild-type (WT) controls." (PMID 29440631, 2018). "In conclusion, these observations have provided evidence that Wnt/beta-catenin activation in combination with KRAS mutations leads to a more aggressive form of lung cancer with an embryonic progenitor phenotype." (PMID 30060526, 2018). "The prevalence of various KRAS mutants in lung cancer is largely mediated by the mutational processes that lead to lung cancer initiation." (PMID 30060526, 2018). "Complementing this work, studies with mouse models have directly confirmed that treatment with distinct mutagens found in cigarette smoke leads to different mutational signatures in lung cancers associated with mutation of the common driver oncogene KRAS." (PMID 29945886, 2018). "A study in lung cancer found a genetic context to the dual effects of ZEB1 with ZEB1 serving as an oncogene in KRAS-mutated lung cancer but as a tumor suppressor in EGFR-mutated lung cancer cells." (PMID 32309604, 2018).
lung cancer (continued). "In the present study, krukovine exhibited a cytotoxic effect and inhibited the growth and proliferation of two KRAS-mutated lung cancer cell lines." (PMID 30186180, 2018). "Induction of mutant KRAS reduces the numbers of viable lung cancer cells harboring KRAS or EGFR mutations, and the effects can be rescued by inhibiting ERK (A) Reduced numbers of viable LUAD cells after activation of KRAS." (PMID 30475204, 2018). "Genetic changes of other genes have been identified, but EGFR, ALK and KRAS mutations are the most frequent mutations in lung cancer." (PMID 30680072, 2018). "There is little available data on the KRAS mutational status in primary lung cancers as compared to that in their brain metastases." (PMID 29868480, 2018). "No parameters were identified that was predictive or significantly correlated to the KRAS mutation in lung cancer." (PMID 28881771, 2017). "Overexpression of miR-1343-3p and reduced expression of miR-671-3p, miR-103a-3p, let-7e, and miR-342-3p were especially distinctive in the ALK-rearranged lung cancer compared with EGFR-mutated and KRAS-mutated lung cancer." (PMID 29189709, 2017). "Kirsten rat sarcoma (KRAS) gene mutation is one of the key drivers for lung cancer development, and is detected in 6–30% of non-small-cell lung cancer (NSCLC) patients." (PMID 28950878, 2017). "Mutated KRAS genes are frequently found in human cancers, especially in approximately 30% of lung cancer." (PMID 29184501, 2017). "For instance, oncogenic KRAS-driven lung cancer has been almost exclusively modeled using knock-in alleles in which Cre-mediated or spontaneous recombination leads to KrasG12D expression." (PMID 29233960, 2017). "Subgroup analysis indicated that lung cancer patients with KRAS mutations had a significantly shorter OS and PFS compared to wild-type lung cancer patients." (PMID 28415658, 2017). "Detecting KRAS mutations in lung cancer is useful for predicting patient outcomes and targeting therapy and tumor tissue is currently used for this assay." (PMID 28415658, 2017). "According to comprehensive reviews a generally high but variable (61-100%) concordance for driver mutations (EGFR and KRAS) between primary tumours and metastases has been reported for lung cancer." (PMID 28347348, 2017). "This is the first meta-analysis to evaluate KRAS mutations in blood samples for treating lung cancer." (PMID 28415658, 2017). "It is therefore important to understand the occurrence of EGFR and KRAS mutations when deciding the initial treatment for lung cancer." (PMID 28422979, 2017). "Whereas ZEB1 promoted growth in KRAS-mutated lung cancer cells, ZEB1 expression suppressed cell growth in EGFR-mutated lung cancer cells." (PMID 28587302, 2017). "Although KRAS mutation has been established as a potential biomarker for predicting the efficacy of erlotinib in lung cancer, little is known about a predictive marker for EGFR TKIs in HNSCC." (PMID 28134774, 2017). "In conclusion, lung cancer is a leading cause of cancer-specific mortality around the world and with the rapid development of liquid biopsy, CTCs and ctDNA provide a novel method for assaying KRAS mutations in lung cancer." (PMID 28415658, 2017). "In the present study, we successfully generated lung CSC-like-cells by introducing defined factors into a KRAS-mutated lung cancer cell line (A549) and made lung cancer organoids that resembled bona fide human lung cancer tissues." (PMID 28951614, 2017).
lung cancer (continued). "Of direct interest to pancreatic cancers, which have very high penetrance of KRAS mutations, targeting metabolic enzymes has been shown to be effective in treatment of KRAS mutant tumours in pre-clinical models of lung cancer." (PMID 28163917, 2017). "The KRAS polymorphisms have been reported to influence the sensitivity and prognosis of various cancers of anti-targeted drug therapy, including lung cancer, gastric cancer, triple-negative breast cancer." (PMID 28328959, 2017). "The forces driving the spectrum of KRAS mutations in human lung cancer appear to be less centralized than in cancers of the pancreas." (PMID 29233960, 2017). "In a recent trial of lung cancer patients, ctDNA outperformed CTCs for detection of the KRAS mutation, revealing sensitivities of 96% and 52%, respectively." (PMID 28054963, 2017). "ALK-rearranged lung cancer had a unique microRNA expression profile that was distinct from that of EGFR- and KRAS-mutated lung cancers." (PMID 28035073, 2017). "Overall, smoking status was the most significant factor for the presence of the EGFR and KRAS mutations in lung cancer." (PMID 28881771, 2017). "In lung cancer, the mutation of KRAS promotes β-oxidation of FAs and the conversion of FAs into the acyl-CoA of FAs, which serve as substrates for lipid synthesis." (PMID 28931870, 2017). "Many retrospective studies in colon and lung cancers have demonstrated poor clinical outcomes as a result of treatment with EGFR tyrosine kinase inhibitors in patients harbouring KRAS mutations." (PMID 28445400, 2017). "The results showed that treatment with honokiol led to a reduction in c-RAF, ERK, and AKT phosphorylation in three KRAS mutated lung cancer cell lines." (PMID 28443025, 2017). "Regarding the prognostic value of KRAS mutation levels in the plasma of lung cancer patients, discordances are reported and were recently reviewed by Garzón and colleagues." (PMID 28146051, 2017). "The multivariate analysis showed never-smoker smoking status was the only significant factor for EGFR mutation, and that current and former smoker status was the only significant factor for KRAS mutation in lung cancer." (PMID 28881771, 2017). "Several studies suggest that KRAS mutations should be known prior to using EGFR-TKI therapy for lung cancer patients." (PMID 28415658, 2017). "KRAS is one of the commonly mutated oncogenes in lung cancer, while activated KRAS mutations are detected in 15–30% of patients with NSCLC and predict a poor prognosis in response to treatment regimens." (PMID 28786996, 2017). "Lung carcinoma cell line (A549) and melanoma cell line (A375) were chosen, because they have high incidence of KRAS and BRAF mutations, respectively." (PMID 28262827, 2017). "Whilst previous studies have demonstrated that plasma processing has an impact on DNA yield, our study is the first to investigate the effect of this on lung cancer patient samples looking specifically in a KRAS mutation detection setting." (PMID 26918901, 2016). "For this study, a similar calculation of background noise for the EGFR c.2369C > T change was performed in 179 FFPE lung cancer specimens with an activating KRAS mutation." (PMID 27304188, 2016). "Women have higher susceptibility to cigarette smoke-induced DNA damage and an increased risk for lung cancer, including higher levels of DNA adducts and higher frequency of the KRAS G12C mutation than men." (PMID 26958810, 2016). "Among lung cancer biomarkers, EGFR and KRAS are the most frequently mutated genes in lung cancer patients and have been routinely used as biomarkers for a decade." (PMID 27999344, 2016).
lung cancer (continued). "KRAS mutations frequently occur in many types of human cancers, for example in 70–90% of pancreatic cancer, 30–60% of colon cancer and 15–50% of lung cancer patients." (PMID 27857191, 2016). "Reported in over 90% of pancreatic cancers, 33% of colon cancers, 32% of lung cancers, and 31% of biliary tract cancers, KRAS is mutated in some of the most treatment-resistant solid tumors." (PMID 27634878, 2016). "Establishing the KRAS mutational status of tumor samples is essential to manage patients with colorectal or lung cancer, since these mutations preclude treatment with monoclonal anti-epidermal growth factor receptor (EGFR) antibodies." (PMID 27632281, 2016). "We have determined that Aurora kinase targeting in KRAS-positive lung cancer cells leads to loss of viability through promoting cell cycle arrest at G2 and through activation of apoptosis." (PMID 26842935, 2016). "The KRAS mutation has been used as a predictive marker of low sensitivity to EGFR-TKI in lung cancer cells harboring EGFR activating mutations." (PMID 26919104, 2016). "As such, our findings that ZEB1 distinctly regulates (promotes or suppresses) the growth of lung cancer cells harbouring KRAS or EGFR mutations is an important new observation." (PMID 27456471, 2016). "The female patients smoked much less than male, and showed distinct molecular characteristics such as, higher frequency of EGFR alterations, lower frequency of KRAS mutation and distinct genetic variants in lung cancer susceptibility loci." (PMID 27009843, 2016). "Till date, we have only limited data concerning evaluation of driver mutations incidence (especially EGFR and KRAS genes) in CNS metastases of lung cancer." (PMID 25902737, 2016). "KRAS mutations are observed more frequent in smoking patients with adenocarcinoma (5–40%) than in the other subtypes of lung cancer." (PMID 27008036, 2016). "Activating mutations in KRAS are prevalent in lung cancer and have been causally linked to the oncogenic process." (PMID 26842935, 2016). "In this lung cancer histology, mutations in KRAS and EGFR and ALK translocations account for the 15–25%, 10–35%, and 2–5% of cases, respectively, the two latter being TKRs." (PMID 27528792, 2016). "Discordance mainly concerned KRAS, an oncogene frequently mutated in lung cancer, particularly in smokers." (PMID 26968843, 2016). "ZEB1 is a driver of epithelial-to-mesenchymal transition that usually promotes lung cancer in the context of KRAS mutation." (PMID 27456471, 2016). "The gene KRAS is commonly mutated in lung cancer to encode a constitutively active and oncogenic protein that is well established to initiate and maintain lung tumorigenesis." (PMID 27911940, 2016). "KRAS mutations, however, are very common in lung cancer ranging from 30–50 % of patients and are associated with poor prognosis and therapy resistance." (PMID 26842935, 2016). "Our data also demonstrated that EGFR mutated or KRAS mutated lung cancers are associated with higher nuclear YAP1 expression in comparison to EGFR/KRAS wild type tumors." (PMID 26716514, 2016). "Presently, the focus/target for treating KRAS-mutated lung cancers is against downstream effectors of activated KRAS." (PMID 29282427, 2016). "Multiple early efforts to identify specific RAS inhibitors that are clinically useful against KRAS-mutated lung cancer were unsuccessful." (PMID 29282427, 2016).